EGF (epidermal growth factor)
Diseases named in the same sentence as EGF in open-access papers (continued):
Sharing a sentence is not in itself a finding about the gene and the disease.
cancer (continued). "In several cancer cells, STAT3 promotes the expression of β-subunit genes and participates in epidermal growth factor (EGF)-induced proteasome upregulation." (PMID 32456207, 2020). "We showed that the growth rate of MCF-7 cancer cell line greatly increased after a few days incubation with EGF and MNTN-EGF compared to control cells." (PMID 32194412, 2020). "As their culture medium contains stimulatory additives, we repeated the experiments omitting EGF in one case and in another, replacing the medium (24 h prior) with the DMEM medium used for the cancer cells." (PMID 31980706, 2020). "Overexpression of receptors such as EGFR, transforming growth factor beta (TGFβ) receptor, c-met, and tropomyosin receptor kinase B (TrkB), and growth factors such as EGF, TGF, HGF, and BDNF have been found to drive aggressive and resistant cancer phenotypes." (PMID 33158043, 2020). "This also explains why the combination of Berberine and Costunolide has a synergistic effect on EGF signaling, thereby providing DHW with an additional advantage of inhibiting cancer cell proliferation and treating cancer." (PMID 32298294, 2020). "The target of EGF-TiO2 PEG NPs is the epidermal growth factor receptor (EGFR), which is abnormally overexpressed in many cancer types and plays a key role in promoting cell proliferation and opposing apoptosis." (PMID 33003324, 2020). "Several authors have previously shown that epidermal growth factor (EGF) induces ERK5 activation and nuclear translocation in different cancer cells." (PMID 32209980, 2020). "We used A431 cells, an EGFR-overexpressing cancer cell line, to investigate the change in TiO2 PEG NP cellular uptake after EGF conjugation." (PMID 33003324, 2020). "In this study, we focused on building GRCs using the single cell RNA sequencing (scRNA-seq) data collected from Cook and Vanderhyden (2019) for four cancer cell lines (A549, DU145, MCF7, and OVCA420) treated with EGF, TGFB1, and TNF." (PMID 32391378, 2020). "Here, we detail our findings that cetuximab treatment causes patient-derived CAFs isolated from three human CRC tumors to increase the secretion of EGF, which subsequently leads to increased resistance of CRC cancer cells to treatment." (PMID 32481658, 2020). "For instance, ligation of EGFR by EGF induces endogenous production of intracellular reactive oxygen species (ROS) and H2O2 in cancer cell lines." (PMID 33087132, 2020). "EGF is a ligand capable of binding to EGF receptor (EGFR) and regulates cell growth, differentiation, migration, invasion, and tumorigenesis in various cancer types, including liver cancer." (PMID 32376896, 2020). "Many factors, such as TGF-β, activating protein-1 (AP-1) and EGF, interact with the promoter of MMP9 and MMP2 to induce the expression of MMP9 and MMP2 in cancer cells." (PMID 32637415, 2020). "HNSCC cells interact with monocytes and induce their polarization into TAMs, which secretes EGF and TGFβ, promoting the EMT of cancer cells." (PMID 32344813, 2020). "Further developing inhibitors that hinder EGF/CSN6/COP1‐mediated FOXO4 degradation and functions can be a strategy for rational cancer therapy." (PMID 33101846, 2020). "In this paper, we showed that EGF conjugation increased the safety and cellular uptake of TiO2 PEG NPs when used on EGFR-expressing cancer cells via their interaction with EGFR." (PMID 33003324, 2020). "To investigate the role of ANXA2 in the regulation of EGF/EGFR signaling, we established cancer cell lines depleted of ANXA2 (A549, HT1080 and MDA-MB-231 ANXA2 knockdown (KD)) and respective controls (ANXA2 scramble)." (PMID 30959964, 2019). "Growth factors including VEGF, PDGF, EGF, TGF‐β, and FGF from TAMs are widely regarded as a potential mediator to promote the survival and proliferation of cancer cells, which can be secreted by fibroblasts." (PMID 31222971, 2019). "Overexpression and aberrant activity of the EGF and EGFR have been observed in various cancer types." (PMID 30971297, 2019).
cancer (continued). "To evaluate whether EGF-induced EGFR-c-Src activation is critical for the phosphorylation of Y328 and Y331 on HDAC3 and determine its association with the malignant behavior of cancer cells, we transiently transfected EGFR in MCF7 cells, which express low levels of EGFR." (PMID 31430896, 2019). "To show that EGFR ligands do not affect the phosphorylation of ErbB3, we investigated the phosphorylation of EGFR and ErbB3 in cancer cell lines treated with EGF, transforming growth factor-α (TGF-α), or heparin-binding EGF-like growth factor (HB-EGF)." (PMID 31615015, 2019). "In cancer cell lines SW480 and HCT116, K49 deacetylation was necessary for epidermal growth factor (EGF)-induced nuclear localization of β-catenin." (PMID 30935091, 2019). "In LUAD, we showed here that EGF-induced phosphorylation of TGIF2 promoted OCT4 transcription and enhanced the stemness of cancer cells." (PMID 31871777, 2019). "Macrophages as well as cancer cells exhibited altered secretome, such as upregulated expression of TGF-β, EGF and M-CSF." (PMID 30927923, 2019). "In response to EGF (Epidermal growth factor) stimulation, the ERK5/MEF-2 pathway subsequently induces DDIAS expression to promote the invasion of cancer cells by activation of various β-catenin target genes." (PMID 31105874, 2019). "It functions as a co-receptor for semaphorins and for multiple growth factors including VEGF, TGF-β, EGF, FGF, HGF and PDGF, resulting in versatile and diverse biological roles encompassing axon guidance, angiogenesis, wound healing, cancer and immunity." (PMID 31208428, 2019). "It has been demonstrated that there is angiogenesis-dependent crosstalk between the EGF and the VEGF pathway in several types of cancer cells." (PMID 31717527, 2019). "It shows that in in vitro experiments using cultured cancer cells, various flavonoids effectively suppress IFN-γ or EGF mediated induction of PD-L1." (PMID 31783532, 2019). "Various signaling pathways (e.g., VEGF, EGF, FGF, and HGF) are significantly included in cancer tissue angiogenesis and ensure the heterogeneity of blood vessel structures." (PMID 30970626, 2019). "The activation of CAFs can be induced by cytokines secreted by cancer cells, including TGF-β and several RTK signaling ligands such as EGF, PDGF and FGF2." (PMID 31671542, 2019). "As for EGF-induced EMT, we focused on transcription repressors of E-cadherin, TWIST, SLUG, and SNAIL; the results showed that cancers express high levels of TWIST, which can be further enhanced by EGF." (PMID 31126310, 2019). "On this note, ADAM17 is associated with shedding of several EGFR family ligands (e.g., EGF, TGFα, and amphiregulin) in NSCLC and other cancers." (PMID 30833304, 2019). "A number of common and cancer type-specific driver pathways have been identified, including the TGFB, EGF, Notch, and HIF-1a pathways." (PMID 31798960, 2019). "TAMs produce soluble growth factors (i.e., HGF, EGF, TGFβ, PDGF, etc.)and inflammatory cytokines (IL-1β, IL-6, and TNFα) that can induce EMT in cancer cells." (PMID 31772577, 2019). "Conclusion:111In-EGF-LP-Dox designed for concurrent chemo-radionuclide therapy showed specificity for and cytotoxicity towards EGFR-overexpressing cancer cells." (PMID 31534505, 2019). "Growth factors can induce COX-2 expression in both normal and cancer cells, including insulin-like growth factor (IGF), transforming growth factor-α (TGF-α) and epidermal growth factor (EGF)." (PMID 31853218, 2019). "We have previously demonstrated that NRP-1 acts as a multiple co-receptor to promote the proliferation of cancer cells by activating the VEGF/VEGFR2 (VEGF receptor 2), EGF/EGFR (EGF receptor) and HGF/c-Met pathways." (PMID 31572065, 2019). "We focused on four well-established EMT-inducing agents, EGF, HGF, IGF-1, and TGF-β1, whose secretion by the cancer cells was higher than that by the PMCs." (PMID 31086083, 2019).
cancer (continued). "Another study identified signaling events coordinated by EGF and a specific ITG that regulates the invasive behavior of carcinoma cells." (PMID 31182680, 2019). "Thereby, EGF and EpEX compete for binding to EGFRex, and EpEX modulates the strength of EGFR signaling to pERK1/2/Slug, repressing EMT in cancer cells." (PMID 30261040, 2018). "In cancer cells, 1,25(OH)2D/VDR activates cyclin-dependent kinase inhibitors (e.g., p21, p27), inhibits mitogenic growth factors such IGF-1 and EGF, and promotes the activity of TGF-β, thus inhibiting cell proliferation and cancer growth." (PMID 29951549, 2018). "We found that STAT3 activation (phosphorylation) and LGR5 mRNA levels were individually induced by EGF, revealing that EGFR is capable of exacerbating cancer stemness properties; this finding is consistent with that of a previous study." (PMID 30068339, 2018). "TGFα and EGF stimulate EGFR to induce cell growth signaling in normal condition and are involved in invasive and metastatic condition of cancers." (PMID 30774817, 2018). "HT29 cancer cells were treated with either DMSO, 50 μmol/L of ginsenoside Rb2 alone or 50 μmol/L of ginsenoside Rb2 together with EGF." (PMID 30264477, 2018). "The ligation of EGFR by epidermal growth factor (EGF) induces endogenous generation of intracellular ROS and H2O2 in the cancer cell line." (PMID 29890617, 2018). "Similarly, EGF-induced ERK activation was previously found to be enhanced and/or sustained in T-REx293T cells expressing NS-associated RIT1 mutants, and ectopic expression of NS- and cancer-related RIT1 mutants in PC6 cells induced phosphorylation of both MEK and ERK." (PMID 29734338, 2018). "On the other hand, PSCs stimulate cancer cell proliferation by production of paracrine factors as TGF-β, FGF2, PDGF, and epidermal growth factor (EGF) and inhibit apoptosis." (PMID 30662458, 2018). "In both these studies, the efficacy of MNT-delivered AEEs targeted at cancer cells with EGFR overexpression was compared with the efficacy of the same AEEs (125I and 67Ga) attached to EGF." (PMID 30210340, 2018). "MAP4K1 (Mitogen-Activated Protein Kinase Kinase Kinase Kinase 1), which is involved in multiple immune and cancer-related pathways including B cell receptor signaling, JNK, EGF/EGFR, TGF-β, and MAPK signaling, was also regulated by the five TFs." (PMID 30594216, 2018). "AREG/EREG overexpression and activation of the EGF pathway is a feature of CIN-positive CRCs, especially for carcinomas of the distal colon." (PMID 30563495, 2018). "However, whether EGF increases growth in cancer tissues during after radiotherapy remains unknown." (PMID 27935858, 2017). "The EGF-CFC family molecule TDGF1 (Cripto, CR-1) plays important roles in the tumorigenesis and aggressiveness of many cancers." (PMID 28620148, 2017). "Cancer cells resistant to chemotherapy and oncoprotein-targeted drugs display increased IL-1α, IL-6, IL-8, TNF-α, HGF, EGF, VEGF, GM-CSF and SDF-1α expression." (PMID 28928376, 2017). "As mentioned in the results section, PLD network involves proteins such as LPAR4, LPAR6, HCRTR1, and GRM5, as well as pathways like EGF/EGFR SP, which their roles have been proven in initiation and progression of several cancers." (PMID 29062084, 2017). "Regarding SCLC a dramatic reduction of EGF, CAL and MMP-9 levels in limited SCLC prevents the distinction from non-cancer patients." (PMID 28117344, 2017).
cancer (continued). "In summary, we have identified a large number of EGF inducible lincRNAs and shown that one of these, EINCR1, is potentially important in the context of human cancer." (PMID 28732076, 2017). "Earlier study has shown that EGF stimulation induced PKM2–β-catenin interaction and translocation into the nucleus in multiple types of cancer cells." (PMID 29162853, 2017). "Several recent studies have similarly shown that Shp2 is required for TGF-β, EGF, or PDGFRα-driven EMT, in various types of cancers." (PMID 28208810, 2017). "These cellular processes are responsible for all the important aspects of the development and progression of cancers including PDAC, therefore abnormally hyper-activated MAPK and AKT pathways by elevated EGF signaling are often observed in PDAC." (PMID 28388589, 2017). "In vitro biomolecular gradients of growth factors such as epidermal growth factor (EGF) in 3D hydrogels also presents chemical concentrations with different spatial and temporal distributions that affect cancer cell response." (PMID 29196753, 2017). "EGF can activate the RAS–RAF–MEK–ERK pathway, and high levels of EGF and constitutive activation of the RAS–RAF–MEK–ERK pathway are observed in cancers." (PMID 29212253, 2017). "In addition, BMI1, through indirect mechanisms, can upregulate genes that promote cancer progression, such as the kinase Aurora A, and several genes involved in epithelial‐to‐mesenchymal transition and transforming growth factor‐β and epidermal growth factor/platelet‐derived growth factor pathways." (PMID 28079973, 2017). "The upstream regulators of these functions were predicted to involve the growth factors TGFB1, EGF, HGF and IGF1, which have known roles in activating these cancer progression pathways." (PMID 27965461, 2017). "Epiregulin is a member of the epidermal growth factor (EGF) family that, upon binding to the EGF receptor (EGFR), stimulates proliferative signalling in cancer cells." (PMID 29208911, 2017). "The majority of EGF inducible protein coding genes show a general reduction in expression in these cancer samples (as exemplified by FOS), and the same was observed for EGF-inducible lncRNAs." (PMID 28732076, 2017). "There was also a significant enrichment in the signaling pathway “Pathways in cancer” among the predictors of TS12 at 24h: genes frizzled class receptor 5 (FZD5) and epidermal growth factor (EGF)." (PMID 28359318, 2017). "NSCLC-specific pathways included MAPK64,65, PI3K-Akt66, PLD36, Ras67, EGF/EGFR68–71, c-Met72–74, LPARs75, IL-476 and IL-677–79 SPs which play significant roles in tumorigenesis and cancer development." (PMID 29062084, 2017). "Epidermal growth factor (EGF) and vascular endothelial growth factor (VEGF) are important in human cancers." (PMID 29036271, 2017). "In the current study, we investigated the potential role of glucose metabolic reprogramming in EGF-induced EMT and cancer stem-like properties in OSCC cells." (PMID 27926487, 2017). "Because EGF–EGFR signaling can promote either cell survival or death, it is an oversimplification to state that EGFR activity increases survival in cancer cells." (PMID 27935858, 2017). "For example, TAMs secrete growth factors including EGF, PDGF and VEGF to promote cancer cell proliferation and blood vessel formation." (PMID 28178994, 2017). "TAMs accordingly produce multiple growth factors (HGF, EGF, TGF, PDGF, etc.)and inflammatory cytokines (IL‐1β, IL‐6, and TNF‐α) that each can induce EMT in cancer cells." (PMID 28599100, 2017). "In digestive cancer cells, activated cathepsins hydrolyze growth factors, such as EGF, VEGF, and TGFβ, to induce their maturation and promote cancer cell proliferation." (PMID 28402938, 2017).
cancer (continued). "The aim of this study was to clarify the effects of epidermal growth factor (EGF) on the uptake efficiency of polystyrene nanoparticles (PS NPs) by A431 cells, a human carcinoma epithelial cell line." (PMID 28629179, 2017). "Paracrine loops of colony-stimulating factor-1 (CSF-1)/EGF and granulocyte-macrophage colony-stimulating factor (GM-CSF)/CCL18 between carcinoma cells and macrophages have been shown to lead to increased carcinoma cell invasion." (PMID 28143526, 2017). "Bio-functionalization of nanoparticles with EGF has been applied to specific targeting cancer cells, which overexpress EGFR and therefore, with ample interest for photothermal cancer treatment." (PMID 27788212, 2016). "TAMs also secrete epidermal growth factor (EGF) in response to macrophage colony-stimulating factor (MCSF), which is released by cancer cells and helps them proliferate." (PMID 27851813, 2016). "Once recruited into the tumor microenvironment, myeloid cells upregulate a number of different growth factors such as EGF, FGF2 and platelet-derived growth factor to promote cancer growth and progression." (PMID 26956475, 2016). "In conclusion, SMAD4 homozygous deletion favors the constitutive activation of ERK, the EGF-induced activation of NF-κB and PI3K/AKT, and the EGF-induced inhibition of Wnt/β-catenin pathways, which are critical to cancer proliferation and metastases." (PMID 27655713, 2016). "For instance, we determined that EGF and IGF-I, insulin and further tumorigenic factors like hypoxia and endothelin-1 up-regulate GPER expression in diverse cancer cell contexts." (PMID 27384677, 2016). "We provide evidence that EGF- and HGF-induced phenotypic changes, ultimately leading to cancer-related death, are dependent on MCT1 expression, independent of MCT1 transporter activity." (PMID 27127175, 2016). "Although some studies showed that RAB35 has the opposite effect on the migration in some kind of cancer cells, in the present work, we found that EGF induced RAB35 activation, while blocking RAB35 expression greatly abolished EGF-induced cell invasion." (PMID 27430308, 2016). "Collectively, these data suggested that EGF induced EMT and cancer cell migration through ERK1/2-phospho-Smad2/3-Snail signaling pathway." (PMID 27829223, 2016). "A fusion of EGF and the catalytic and translocation domains of DT (DAB389EGF) killed multiple human cancers at pM concentrations." (PMID 27153091, 2016). "Multiple signals are responsible for induction of EMT in cancer cells; in particular, hepatocyte growth factor (HGF), epidermal growth factor (EGF), and transforming growth factor-β (TGF-β)." (PMID 26925388, 2016). "Src kinase activity is necessary for EGF and other HER ligand signaling to signal transducer and activator of transcription (STAT) and MAPK pathways in various cancers." (PMID 26919242, 2016). "Several of the enriched pathways reported herein, i.e., focal adhesion, EGF-EGFR, signaling by ERBB2, angiogenesis etc. have been documented to be of importance not only in human iUC, but in several other human cancers." (PMID 26352142, 2015). "This receptor can be activated by diverse ligands; namely, EGF, transforming growth factor-α (TGF-α), amphiregulin, betacellulin, heparin-binding EGF, or epiregulin that are locally secreted by cancer cells and can act in an autocrine fashion." (PMID 26510973, 2015). "Nrg1 is one of the most active members of the epidermal growth factor (EGF)-like family, and also is considered to be a cancer related cytokine." (PMID 25560389, 2015). "EGFR and EGF-EGFR signaling has been documented to be of critical relevance in iUC, and in other human cancers as well." (PMID 26352142, 2015). "Epidermal growth factor (EGF) activates mRNA and promoters of COX-2 in cancer tissues, and COX-2 induction by EGF is suppressed by inhibition of kinases including PI3K, mitogen-activated protein kinase (MAP2K), and p38 MAPK." (PMID 25734181, 2015).